CDK6 (cyclin dependent kinase 6)
Diseases named in the same sentence as CDK6 in open-access papers (continued):
Sharing a sentence is not in itself a finding about the gene and the disease.
breast cancer (continued). "UALCAN cancer database analysis indicated that the expression of cdk4 and e2f1 in breast cancer was significantly higher than that in normal tissues (p < 0.01), while the expression of cdk6 and rb1 was not higher than that in normal tissues." (PMID 32357912, 2020). "Importantly, palbociclib, a small‐molecule inhibitor of CDK4 and CDK6, combined with letrozole has recently been approved to treat postmenopausal women with ER‐positive, HER2‐negative advanced breast cancer as a first‐line therapy." (PMID 30714150, 2019). "Acquired CDK6 amplification has resulted in breast cancer resistance to CDK4/6 inhibitors; however, the reason for CDK6 overexpression resulting in resistance to CDK4/6 inhibitors remains unclear." (PMID 31448056, 2019). "The combination of palbociclib, a selective inhibitor of the cyclin-dependent kinases CDK4 and CDK6, and ovarian suppression with letrozole significantly prolonged progression-free survival in women with ER+/HER2– advanced breast cancer in the PALOMA-3 (NCT01942135) study." (PMID 32039034, 2019). "We scored different levels of CDK6 expression in these tumor samples and found that high CDK6 expression correlated with recurrent disease in patients with ER + /PR + /HER − luminal subtype of breast cancer." (PMID 30518851, 2018). "Cell lines in which CDK4 knockdown but not CDK6 knockdown had a pronounced effect on growth were enriched for those derived from breast cancers." (PMID 30443290, 2018). "In breast cancer, CDK4 and CDK6 are among the most well studied CDKs." (PMID 29228549, 2017). "Our data also rule out CDK6 in the maintenance of breast cancer stemness and indicate that CDK4 is the predominant regulator of cancer stemness, thereby representing a unique and specific prognostic marker for basal-like TNBC patients." (PMID 27759034, 2016). "Similarly, miR-22 targets CDK6, SIRT1, and Sp1, which are genes involved in the senescence program, and induces cellular senescence in both human fibroblast and breast cancer cells." (PMID 24282530, 2013). "The function of cyclin D1 in mammary oncogenesis in mice is mediated through the activation of its regulatory partner CDK4, as mice lacking CDK4 or expressing the CDK4/CDK6-specific inhibitor INK4A are resistant to HER2-induced mammary tumor formation." (PMID 23786849, 2013). "A recent study is consistent with our results, as chemical inhibition of CDK4 and CDK6 in breast cancer cells did not influence double-strand break repair after irradiation." (PMID 23886499, 2013). "Data from DepMap, where ER+ breast cancer cell lines underwent systematic gene silencing to identify genes essential for survival, show that CDK4 knockout yields much lower DepMap CRISPR CERES scores than CDK6 knockout, indicating stronger dependency on CDK4 than CDK6 for viability." (PMID 41226361, 2025). "In addition, MCF-7 breast cancer cells accumulated in the G1 phase upon the KD of TRPC1, which was also found in the thyroid cancer cell line ML-1, where the expression of the CDK6, Cyclin D2, and D3 decreased, and the expression of their regulating inhibitor p21 increased." (PMID 35887266, 2022). "Interestingly, parkin mRNA and protein expression are significantly decreased in breast cancer, but no significant changes in cyclin D1 and cyclin E levels are observed, while cyclin-dependent kinase 6 (CDK6) expression level is significantly increased." (PMID 36147481, 2022). "Researchers had proved that miR-1296-5p could function as an inhibitor in gastric cancer by targeting cyclin-dependent kinase 6 and epidermal growth factor receptor, ERBB2-positive breast cancer by downregulating ERBB2, in osteosarcoma through repressing notch receptor 2 expression." (PMID 35287543, 2022). "Additionally, we show in breast cancer cells that abemaciclib stabilizes primed CDK4-cyclin D complex and displaces p21, not observed in CDK6-cyclin D models, resulting in altered sensitivity in breast cancer models with greater CDK6 expression." (PMID 36446794, 2022).
breast cancer (continued). "In addition, targeted proteins for breast cancer therapy are also CDK4, CDK6, PARP, PI3K and RAL." (PMID 34361688, 2021). "Among women, the most common type of breast cancer is the hormone receptor-positive/human epidermal growth factor receptor 2 negative (HR+/HER2−-) breast cancer, where CCND1 as an encoding of cyclin D1, the catalytic subunit of CDK4 and CDK6, is profoundly expressed." (PMID 34948218, 2021). "In the STAT3 and Cyclin D pathways, CDK6 could up-regulate the transcription of P16 and the expression of VEGF-A that can promote angiogenesis, contributing to the progression and drug resistance of breast cancer." (PMID 34123801, 2021). "In particular, glioblastoma, breast cancer, colon cancer, melanoma, lung adenocarcinoma, head and neck cancer, pancreatic cancer, liver cancer, and prostate cancer cohorts showed the most significantly (p < 0.001) elevated CDK2, CDK4, CDK6, and STAT3 expressions." (PMID 33668805, 2021). "Palbociclib, a selective inhibitor of CDK4 and CDK6 developed by Pfizer (USA), was demonstrated to be effective in a phase III study involving 521 patients who had hormone-receptor-positive metastatic breast cancer, and FDA approved its application for breast cancer in February 201539,40." (PMID 33009370, 2020). "Our findings suggest that the mechanism of CDK4/6 inhibitor resistance exists in multiple forms and that the levels of CDK4 and CDK6 are potential biomarkers of CDK4/6 inhibitors, which may be especially useful for the selection of patients to estimate the sensitivity in breast cancer." (PMID 31448056, 2019). "Use Case – Triple Negative breast cancer with reported amplification ofRICTOR,CDK6 andMET." (PMID 31608148, 2019). "Furthermore, high CDK6 protein level is tightly correlated to the recurrence of luminal breast cancer, lending further support to the pro-survival role of CDK6 mediated by the FOXO3a-BRD4 complex in luminal breast cancer." (PMID 30518851, 2018). "Evidence from breast cancer mouse models suggests that Cyclin D1, and CDK4 and CDK6 activation contribute to suppressing senescence, as Cyclin D1 ablation in these models after tumor formation led to an onset of senescence in the isolated tumor cells, as did treatment with a CDK4 and CDK6 inhibitor." (PMID 29050219, 2017). "Additionally, Nar altered the expression of apoptosis and cell-cycle regulatory genes by down-regulating Cdk4, Cdk6, Cdk7, Bcl2, x-IAP and c-IAP-2 and up-regulating p18, p19, p21, caspases 3, 7, 8 and 9, Bak, AIF and Bax in both colorectal and breast cancer cells." (PMID 26074733, 2015). "Similarly, CDK6 demonstrated r>0.7 in only 4 cancers (glioblastoma, head and neck cancer, lung adenocarcinoma, and lung squamous cancer) while IGF1R had r>0.7 in only one cancer (breast cancer)." (PMID 24874471, 2014). "Especially in the treatment of patients with hormone receptor (HR)-positive and ERBB2 (formerly HER2)-negative advanced breast cancer, CDK4 and CDK6 inhibitors (abemaciclib, ribociclib, and palbociclib) have an important role." (PMID 36945921, 2023). "In predominantly CDK4-dependent cells (such as estrogen receptor-positive [ER+] breast cancer), abemaciclib, ribociclib, and palbociclib displace p21 from the CDK4/cyclin D1 complex (but not CDK6 from CDK6/cyclin D1)." (PMID 37369022, 2023). "Overall, we inferred that breast cancer with low p21 expression largely depends on the CDK2–cyclin E complex to progress to the S-phase; thus, CDK4 and CDK6–cyclin D complex are no longer necessary to overcome the G1–S checkpoint." (PMID 31448056, 2019). "Palbociclib, an inhibitor of CDK4 and CDK6, in combination with endocrine therapy resulted in improved progression-free survival (PFS) in ERα+/Her2 negative advanced breast cancer." (PMID 29228549, 2017).
breast cancer (continued). "In agreement with the results from the cell-cycle analysis, we found that the protein expression of the negative cell-cycle regulator P21 was markedly increased in breast cancer cells after ZLM-7 treatment, which was accompanied with decreased expressions of cyclin D1, CDK2 and CDK6." (PMID 35890172, 2022). "Meanwhile, in the last decade, CDK4/CDK6 inhibitors have been developed as novel anticancer agents, especially for hormone receptor-positive/human epidermal growth factor receptor-2 negative (HR-positive/HER2-negative) metastatic and advance breast cancer." (PMID 34361615, 2021). "The recent addition of cyclin-dependent kinase 4 (CDK4) and CDK6 inhibitors to endocrine therapy has remarkably improved the outcome of patients affected with hormone receptor positive (HR+), human epidermal grow factor receptor 2 negative (HER2 -) advanced breast cancer (ABC)." (PMID 35223478, 2022).
glioma (101 papers, 2006 to 2026). A benign or malignant brain and spinal cord tumor that arises from glial cells (astrocytes, oligodendrocytes, ependymal cells). "By inhibiting CDK4 and CDK6, p16 impedes cell cycle progression from G1 to S phase and acts as a tumor suppressor that has been implicated in the prevention of cancers, notably gliomas." (PMID 29489901, 2018). "Finally, we visualized the close association between CDCA3 and common glioma cell cycle checkpoint markers, including CDK6, CDK4, CDK2, CDK1, CDKN3, and CDKN2C, using circos plots." (PMID 38728485, 2024). "Up-regulation of CDK6 could abrogated the biological behavior changes in glioma cells caused by miR-200a." (PMID 34796112, 2021). "Modulating SNHG15/CDK6/miR-627 axis by palbocicli could reduce M2-polarization of glioma-associated microglia in GBM multiforme and finally could overcome TMZ resistance." (PMID 34178658, 2021). "There is a negative correlation between the expression level of miR-124 and that of CDK4 and CDK6 in glioma samples." (PMID 40134003, 2025). "Sixty glioma-associated targets were associated with CHR, such as MDR transporters (ABCB1, ABCC1, ABCG2), cyclin-dependent kinases (CDK1, CDK6), matrix metalloproteinases (MMP2, MMP9, MMP12), and genes related to inflammation or oxidative stress (NOS2, NOX4)." (PMID 40963691, 2025). "A related study found that hepatogenic growth factor acts in conjunction with c-Jun to induce CCND1/CDK4/CDK6 expression and promote the proliferation of gliomas." (PMID 40138292, 2025). "PDGFRA and CDK6 amplification were enriched in diffuse hemispheric gliomas when compared to other adult-type gliomas." (PMID 39842935, 2025). "CDCA3 is closely associated with many classic glioma biomarkers (CDK4, CDK6), and inhibitors of CDK4 and CDK6 have been shown to be effective in tumor therapy." (PMID 38728485, 2024). "In previous studies, it has been widely verified that high expression of MCM7 or CDK6 is closely related to the malignant proliferation of glioma cells." (PMID 37005685, 2023). "miR-137 is a well-known suppressor of cell proliferation, mainly by regulating the cell cycle and enhancing differentiation of glioma stem cells via its downstream targets, such as Clcl12, Cox2, Pdgfr, Sp1, Tcf4 and/or Cdk6." (PMID 38138985, 2023). "Cdk6 protein levels are elevated in glioma, but this only leads to tumor progression after post-translational modification by SUMOylation, which stabilizes and enhances the kinase activity driving the cell cycle." (PMID 35572197, 2022). "The suppression of UBC9 by miR-214 overexpression inhibits the proliferation of glioma cells, and the stabilization of cyclin-dependent kinase 6 (CDK6) by SUMO-1 modification drives the cell cycle for glioblastoma development and progression." (PMID 35408841, 2022). "In glioma, the LINC00473/miR-637/CDK6 axis promotes the proliferation and invasion of glioma cell lines." (PMID 36175921, 2022). "Results showed that either PCGEM1 knockdown or miR-539-5p mimics suppressed glioma cell proliferation, migration and invasion while CDK6 overexpression reversed the effects of PCGEM1 knockdown." (PMID 33589577, 2021). "Our data showed that silencing BYSL caused cell cycle arrest at G1 phase in glioma cells, which was further verified by the downregulation of cyclin D1 and CDKs (CDK4 and CDK6) and the upregulation of CDKIs (P21 and P27)." (PMID 33628587, 2021). "Our analysis of clinical data from the TCGA database indicated that mTOR, STAT3, and CDK6 are collectively hyper-expressed in both low-grade glioma and GBM cohorts." (PMID 34572040, 2021). "In conclusion, our results revealed the interaction of H19, miR-200a and CDK6/ZEB1 in glioma cells, which can affect tumor progression." (PMID 34796112, 2021).
glioma (continued). "Up-regulation of CDK6 was able to induce the proliferation of U87-MG cells, and vice versa, inhibition of CDK6 expression suppress the growth of glioma cells." (PMID 34796112, 2021). "MiR-539-5p mimics repressed glioma progression while CDK6 overexpression reversed the roles of PCGEM1 knockdown." (PMID 33589577, 2021). "It negatively correlates with patient survival and low expression of CDK6 can significantly enhance the sensitivity of gliomas to chemotherapy." (PMID 34615480, 2021). "Consistently, our results also showed that CDK6 overexpression promoted the proliferation, migration and invasion of glioma cells." (PMID 33589577, 2021). "Knockdown of UCA1 inactivates the MAPK signaling pathway by downregulating CDK6 expression mediated by miR-193a, which decreases the proliferation and promotes the apoptosis of glioma cells." (PMID 33777227, 2021). "It has also beendemonstrated that exogenous administration of proapoptotic miR-218 suppressesexpression of cyclin-dependent kinase 6 (CDK6), reduces proliferation, andcauses apoptotic death of glioma cells." (PMID 34707896, 2021). "These biological behavior changes in glioma cells were dependent on the binding to potential target genes including CDK6 and ZEB1." (PMID 34796112, 2021). "UCA1 knockdown inhibits proliferation and migration of glioma cells through miR-193a-mediated downregulation of cyclin-dependent kinase 6 (CDK6), and inactivates the PI3K/AKT pathway by decreasing the expression levels of phosphorylated PI3K and AKT proteins." (PMID 33777227, 2021). "We found that TFs encoded by HOX genes recurrently appeared in glioma, and these TFs regulated critical genes (such as MAML2, CDK6, FAM84B, and PTBP1)." (PMID 33537074, 2021). "Summarily, our findings suggest that PCGEM1 plays oncogenic functions in glioma cells through modulating miR-539-5p/CDK6 pathway." (PMID 33589577, 2021). "Compared with normal tissues, we found that MAML2, FAM84B, and CDK6 exhibited higher expression in glioma." (PMID 33537074, 2021). "In our study, mRNA level of Cdk2, Cdk4 and Cdk6 down-regulated in MPT0B291-treated glioma cells indicating that HDAC6 inhibitor transcriptionally regulates those cyclin-dependent kinases." (PMID 33162824, 2020). "In gliomas, the SUMOylation of CDK6 inhibits ubiquitin‐mediated degradation of CDK6, stabilizes CDK6 protein, regulates the cell cycle, and ultimately drives the development of gliomas." (PMID 32997416, 2020). "The combination therapy of CDK4/CDK6 and mTOR inhibitors resulted in the synergistic growth arrest of diffuse bridge glioma cells." (PMID 32508030, 2020). "Among the selected genes, 15 (Araf, Braf, Kras, Ccnd1, Cdk6, Igf1r, Nras, Pik3ca, Pik3r1, Pdgfra, Pdgfrb, Pdgfb, Akt1, Akt2, and Mdm2) were related to glioma and leukemia." (PMID 31523185, 2019). "Reduced expression of miR‐34 has been observed in many cancer types 49, including human gliomas, with concomitant increased expression of the target oncogenes c‐Met, Notch‐1/2 and cyclin‐dependent kinase 6 (CDK6)." (PMID 29972883, 2018). "In vitro, inhibitors of CDK6 have been shown to enhance the sensitivity to chemotherapy on glioma cell lines." (PMID 28467792, 2017). "CDK6 has been found to be amplified or overexpressed in glioma, lymphoma, and leukemia, but little is known about CDK6 expression in HCC." (PMID 26498144, 2016). "To further explore the possible mechanism by which RACK1 promoted the glioma cell cycle, we then investigated the protein levels of G1/S transition key regulators, such as Cyclin D1 and CDK6." (PMID 27763568, 2016).